GLS2 (glutaminase 2)
Diseases named in the same sentence as GLS2 in open-access papers (continued):
Sharing a sentence is not in itself a finding about the gene and the disease.
tumor (continued). "In contrast, no clear methylation or much lower methylation in GLS2 promoter region was detected in these 3 non-tumor liver tissues." (PMID 24797434, 2014). "Importantly, such a pattern is found to be generally consistent with the relative mRNA level of Gls2 measured in the group of 20 pairs of human primary HCC tissues and adjacent non-tumor tissues." (PMID 24330717, 2013). "To further confirm the pathological relevance of Gls2 promoter hypermethylation in mediating its downregulation in tumorigenesis, we further analyzed the Gls2 promoter methylation in 20 pairs of human primary HCC tissues and adjacent non-tumor tissues." (PMID 24330717, 2013). "Furthermore, some mammalian tissues and tumor cells show co-expression of GLS and GLS2 isoforms, although the physiological meaning of the existence of different GA transcripts is not understood." (PMID 22679499, 2012). "In addition, an MYC-dependent metabolic switch from glutaminase 2 (GLS2) to GLS1 may occur during HCC progression, enabling metabolic rewiring by increasing glutamine uptake and decomposition rate in tumor cells." (PMID 39085965, 2024). "Indeed, the immunohistochemical analysis of the GLS2 level in 112 HCC and 111 adjacent non-tumor tissues (NT) revealed significantly lower GLS2 staining in tumors than in NT tissues; a lack of GLS2 staining correlated with a short survival time." (PMID 38067269, 2023). "Finally, we found that decreased GCN5L1 levels, rather than alterations in GLS1 or GLS2 expression, are associated with human HCC tumours and support that changes in glutaminase activity are important in the pathogenesis of this disease." (PMID 35538890, 2022). "Moreover, tumours with greater elevations in glutaminase activity significantly correlated with decreased GCN5L1 protein levels but not with GLS1 or GLS2 protein levels." (PMID 35538890, 2022). "When biological subtypes were considered, GLS and GLS2 proteins remained positively correlated, albeit weakly, in the high proliferation/luminal B tumours (p = 0.045), but not the low proliferation/luminal A tumours (p = 0.115)." (PMID 34439127, 2021). "In non-hypoxic conditions, ID1 supports tumor cells by upregulating GLS2 and glutamine metabolism." (PMID 34820369, 2021). "Moreover, the biosynthesis of serine and glycine affects cellular antioxidative capability and also promotes tumor growth; The c-MYC oncogene activates the expression of glutaminase (GLS1/GLS2) and glutamine metabolism in cancer cells, and glutamine can be converted to glutamate even in hypoxia." (PMID 33849550, 2021). "While overwhelming evidence points to GLS isozymes as oncogenic proteins, underlying metabolic reprogramming leading to cancer growth and proliferation in Gln-addicted tumors, the role of GLS2 isozymes in tumor biology has not yet been elucidated and needs further clarification." (PMID 32042057, 2020). "Specifically, the GLS2 isoform showed a negative correlation for with tumor grade, opposite to GLS1, suggesting distinct and antagonistic roles depending on the tumor differentiation status." (PMID 41439982, 2025). "The experiments show that GLS2, but not GLS1, can directly bind to a protein called Rac1 that normally promotes the spread of tumor cells around the body." (PMID 26751560, 2016). "Subsequent immunochemistry staining confirmed that expression of GLS2, but not GLS1, was markedly elevated in MYCN-amplified tumors (samples 27, 9638 and 35313) when compared with the low-stage, non-amplified tumor (sample 20641)." (PMID 26528759, 2015). "To investigate the expression and biodistribution of GLS1 and GLS2 in HCC, we performed immunohistochemical staining for GLS1 and GLS2 on the first group of paired tumor tissues (TT) and adjacent none tumor tissues (NT) from HCC patients." (PMID 25844758, 2015). "However, GLS2 protein (p = 0.006), but not GLS, was predictive of a longer recurrence-free interval, which remained independent of tumour size, grade and nodal stage (p = 0.003)." (PMID 34439127, 2021).
cancer (86 papers, 2011 to 2025). A tumor composed of atypical neoplastic, often pleomorphic cells that invade other tissues. "The study revealed that deficiency in GLS2 can lead to resistance to ferroptosis in human cancer cells, cells from Gls2 knockout mice." (PMID 39315094, 2024). "The glutaminase enzymes GAC and GLS2 have both been implicated in cancer progression due to the upregulation of their expression and catalytic activities." (PMID 38438397, 2024). "In contrast, other studies demonstrated the oncogenic activity of GLS2, where its overexpression is associated with poor overall survival in blood, colorectal, ovarian and thymoma cancers." (PMID 32326003, 2020). "To this end, we investigated the association of decreased GLS2 expression with cancer metastasis in human HCC samples." (PMID 26751560, 2016). "Our studies demonstrated a correlation between nuclear targeting and the antiproliferative response induced by GLS2 in human cancer cell lines, but further studies are needed to elucidate whether nuclear GLS2 is causatively linked to this response." (PMID 32042057, 2020). "For GLS2, a considerably lower number of positively-correlated genes were associated with colon, head-and-neck, lung, and blood cancer, among which six genes were common in all cancers." (PMID 30871151, 2019). "Moreover, the expression of combined GLS- and GLS2-centered- signature-gene set regulated clinical prognosis in certain cancers which further predict that the functional partners of GLS and GLS2 contribute to significant CNAs and mutations and subsequently regulate the clinical outcomes in cancers." (PMID 30871151, 2019). "Moreover, the inhibition of EMT leads to a GLS2-directed metabolic shift in mesenchymal cancer cells, which may make these cells susceptible to chemotherapies." (PMID 31652551, 2019). "Furthermore, decreased GLS2 expression is associated with enhanced metastasis in human cancer." (PMID 26751560, 2016). "Understanding GLS2 functions will shed light on its role in physiological conditions and in cancer, where the aim is to identify GLS2 expression as an indicator of certain molecular vulnerabilities to be exploited in future targeted therapies." (PMID 39796278, 2025). "We have identified for the first time specific crosstalk between GLS2 and PDH, placing GLS2 as a potential key regulator of mitochondrial metabolism, linking glucose and glutamine metabolism, essential metabolic pathways for cancer cells." (PMID 39796278, 2025). "Metabolic profiling of human cancer cells revealed that TAp73 transcriptionally regulates glutaminase-2 (GLS-2), thereby influencing serine biosynthesis." (PMID 40649823, 2025). "The glutaminase enzymes GAC and GLS2 catalyze the hydrolysis of glutamine to glutamate, satisfying the ‘glutamine addiction’ of cancer cells." (PMID 38438397, 2024). "Twenty years ago, Turner and McGivan documented, for the first time, co-expression of the GLS and GLS2 genes in a single cancer cell type." (PMID 38067269, 2023). "Other studies have also shown that PTGDS, GREM1, LAMA4, S100A14, PREX2, and GLS2 have potential value in promoting cancer progression and predicting cancer prognosis." (PMID 37306872, 2023). "We found that most of the genes were risk factors in several cancers, except for CTLA4, KCNQ1, and GLS2." (PMID 36860371, 2023). "Elevating GLS2 expression within cancer cells has demonstrated an antiproliferative effect, resulting in cell cycle arrest at the G2/M phase." (PMID 38248716, 2023).
cancer (continued). "Mammalian cells express two GLS isoforms, namely kidney-type glutaminase (KGA or GLS1) and liver-type glutaminase (LGA or GLS2) that are dysregulated in a cancer type-specific manner." (PMID 36768660, 2023). "In contrast, GLS-2 has recently been identified as a key gene in the suppression of cancer metastasis via its regulation of glutamine metabolism." (PMID 38248716, 2023). "In contrast, GLS2 has been reported to function as a tumour suppressor and is usually downregulated in cancer." (PMID 36151426, 2023). "GLS1 is ubiquitously expressed in healthy tissues and many types of cancer, whereas GLS2 is primarily enriched in the liver." (PMID 35538890, 2022). "Based on the evidence that GLS2 facilitates GSH production in several cancer cell lines, GLS2 is recognized as a negative regulator of ferroptosis." (PMID 34568341, 2021). "In this study, we systematically analyzed the gene expression, epigenetic regulation, and genomic alterations of six key GLNM regulators (including SLC1A5, SLC7A5, SLC3A2, SLC7A11, GLS, and GLS2) across 33 different cancer types." (PMID 34573287, 2021). "In the present study, GLS2 expression and overall survival were positively correlated in most of cancers, with GLS2 presenting as a suppressor gene." (PMID 34573287, 2021). "It’s been confirmed that GLS2 has complex connections with cancers, and the up- or down-regulated expression level is significantly associated with patients’ survival in different cancers." (PMID 33602233, 2021). "TP73 regulates the activation of serine/glycine biosynthesis in cancer cells through transcriptional upregulation of glutaminase-2 enzyme (GLS-2)." (PMID 33801846, 2021). "Based on cell line analysis, it was found that the expression of GLS2 was inversely correlated with GLS in 52% of the 33 cancer types." (PMID 34573287, 2021). "GLS isozymes have been consistently related to cell proliferation, but the role of GLS2 in cancer remains poorly understood." (PMID 32042057, 2020). "Then, we performed a cell cycle analysis to detect shifts in the distribution of cancer cells after GLS2 overexpression." (PMID 32042057, 2020). "Upregulation of GLS2 in cancer cells induced an antiproliferative response with cell cycle arrest at the G2/M phase." (PMID 32042057, 2020). "In this work, we extended our previous finding of a nuclear expression for GLS2 in brain cells by showing that GLS2 is located in both mitochondria and nuclei of human cancer cells." (PMID 32042057, 2020). "While GLS upregulation correlates with proliferating stages and malignancy in many types of cancer and experimental tumors, little is known about the role of GLS2 in tumorigenesis." (PMID 32042057, 2020). "While GLS1 is usually upregulated in cancers, the expression of GLS2 is generally repressed in cancers." (PMID 33194749, 2020). "Apart from human cancer cells, we also demonstrated a nuclear location of GLS2 in COS-7 cells ectopically expressing the human protein." (PMID 32042057, 2020). "We then determined the genes correlated with GLS and GLS2 in certain types of cancers in which these glutaminase members are significantly upregulated using the R2 platform." (PMID 30871151, 2019). "The resulting gene expression patterns suggest that GLS and GLS2 are differentially expressed in cancer versus normal tissues and that the magnitude of their expression also varies depending on the tissue type." (PMID 30871151, 2019).
cancer (continued). "The underexpression of GLS2 in these types of cancer was, however, positively correlated with high survival." (PMID 30871151, 2019). "To provide a systematic understanding regarding the role of GLS and GLS2 in cancer prognosis, we performed comparative data mining on numerous gene expression data sets." (PMID 30871151, 2019). "Since GLS2 over-expression in SUM159 cells enhanced glutaminolysis, we examined amino acid utilization in GLS2 over-expressing cancer cells induced to undergo EMT." (PMID 31652551, 2019). "We also found that the expression of GLS2 is inversely correlated with the EMT signature gene expression in 70% of the cancer types analyzed." (PMID 31652551, 2019). "From the TCGA, data we also examined the expression of GLS2 in more than 11,000 patients with 33 different cancer types." (PMID 31652551, 2019). "The expression patterns of GLS2 in different types of cancer are substantially different from that of GLS." (PMID 30871151, 2019). "GLS2 is associated with increased glutathione levels, and GLS2, like GLS1, can regulate the oxidative stress resistance properties of cancer cells." (PMID 31027222, 2019). "The database was successively queried for GLS and GLS2 expression in all the cancers of interest and their respective normal tissues." (PMID 30871151, 2019). "Our multiomics analysis revealed that GLS and GLS2 play distinct roles in cancer development and differentially modulate the clinical outcomes of cancer." (PMID 30871151, 2019). "We individually examined the genetic alterations of GLS and GLS2 in various types of cancer using cBioPortal and subsequently provided a comparative report with respect to the functional protein partners of glutaminases obtained from the PPI network analysis." (PMID 30871151, 2019). "To obtain further insights into the prognostic characteristics associated with glutaminases, we investigated the prognostic values of GLS and GLS2 expression levels for different types of cancer using the ProgonoScan database." (PMID 30871151, 2019). "The varying prognostic characteristics of glutaminases suggest that GLS and GLS2 expression differentially modulate the clinical outcomes of cancers." (PMID 30871151, 2019). "Kidney-type glutaminase (GLS) and liver-type glutaminase (GLS2) are dysregulated in many cancers, making them appealing targets for cancer therapy." (PMID 30871151, 2019). "Unlike GLS, which is active in several types of cancer and is indirectly promoted by c-myc through repressing the expression of miR-23a/b, the role of GLS2 in cancer seems more complex." (PMID 28811348, 2017). "This induced the upregulation of GLS2 (Glutaminase 2), one of the miR-16 targets, which enhanced glutamine uptake and the rate of glutaminolysis, which is known to increase in cancer cells." (PMID 29147648, 2017). "Considering the critical role of Rac1 in cancer, our results provide a novel mechanism for the different roles of GLS1 and GLS2 in tumorigenesis, particularly with respect to cancer metastasis." (PMID 26751560, 2016). "Our results show that GLS2, which catalyzes glutamine to glutamate (a glutathione synthesis precursor), is significantly increased in hypoxic cancer cells." (PMID 26956544, 2016). "GLS2, which catalyzes glutamine to glutamate, was significantly increased in hypoxic HepG2 cancer cells." (PMID 26956544, 2016). "Our findings demonstrate amino acid sequences for selective inhibition of glutaminase isozymes and validate GLS2 as a potential anti-cancer target." (PMID 25026281, 2014). "In contrast to the disease indications of the KGA and GAC (GLS1) inhibitors described for anti-cancer, the biological role of GLS2 is still under exploration." (PMID 25026281, 2014).
cancer (continued). "GLS2 inhibition by either alkyl benzoquinones or GLS2 siRNA reduced carcinoma cell proliferation and anchorage-independent colony formation, and induced autophagy via AMPK mediated mTORC1 inhibition." (PMID 25026281, 2014). "To determine the molecular mechanism by which Gls2 suppressed cancer cell proliferation and colony formation, we further investigated the effect of Gls2 overexpression on cell cycle." (PMID 24330717, 2013). "Overexpression of Gls2 in cancer cells induced phosphorylation of the protein phosphatase cdc25c, a key regulator in the G2/M checkpoint, together with a significant reduction in p21 and cyclin D1." (PMID 24330717, 2013). "In our study, we found that overexpression of Gls2 markedly suppressed cancer cells proliferation and colony formation." (PMID 24330717, 2013). "In contrast, cancer cells with high Gls2 expression exhibit limited effects upon Gls1 inhibition, suggesting that Gls2 may compensate for metabolic flexibility." (PMID 41007265, 2025). "GLS2 has been shown to be silenced in certain cancer cell lines, such as liver and colon cancers." (PMID 41515893, 2025). "Clearly, further investigations are needed to elucidate whether DICER stabilization by GLS2 can also modulate other miRNAs/RNAi, as well as how it influences the cancer cell phenotype." (PMID 38067269, 2023). "Although GLS2 was originally thought to be expressed exclusively in adult liver, several later studies proved its expression in extrahepatic tissues such as brain, pancreas, and human cancer cells, and cells of the immune system." (PMID 38067269, 2023). "GLS2 has been reported as a tumor suppressor in some types of cancer." (PMID 34094960, 2021). "Furthermore, the capacity of GLS2 to alter miRNA patterns in cancer cells would be explained by recent findings showing that GLS2 is involved in miRNA regulation through Dicer stabilization." (PMID 33610185, 2021). "Actually, the expression of GLS2 is also regulated by oncoproteins including N-myc; therefore, GLS2 may display complex and diverse modulatory functions in cancer cells." (PMID 34573287, 2021). "It is expected that phospholipid-GNR might result in dysregulation of enzymes necessary to convert glutamine to glutamate, including the two mitochondrial glutaminases (GLS and GLS2) and consequently could affect diverse functions in cancer cell metabolism." (PMID 33673519, 2021). "Finally, the description of GLS2 as a pro-oncogenic protein has unique implications for the future development of small-molecule-oriented therapeutics targeting glutaminases in cancer." (PMID 33746066, 2021). "Thus, the relationship between expression of GLS2 and cancer proliferation in patients remains controversial." (PMID 34332338, 2021). "We have demonstrated a dual targeting of GLS2 in human cancer cells." (PMID 32042057, 2020).